DPH2 (diphthamide biosynthesis 2)
Description:
Required for the first step of diphthamide biosynthesis, a post-translational modification of histidine which occurs in elongation factor 2. DPH1 and DPH2 transfer a 3-amino-3-carboxypropyl (ACP) group from S-adenosyl-L-methionine (SAM) to a histidine residue, the reaction is assisted by a reduction system comprising DPH3 and a NADH-dependent reductase (By similarity). Facilitates the reduction of the catalytic iron-sulfur cluster found in the DPH1 subunit (By similarity).
Synonyms: DPH2L2; DEDSSH2
Tractability: PROTAC: ubiquitination databases record sites on it; its protein half-life has been measured.
Gene: Protein-coding gene on chromosome 1 (43,969,978 to 43,973,373, forward strand). Ensembl gene ENSG00000132768.
Subcellular location (Human Protein Atlas): Cytosol; Endoplasmic reticulum
Pathways (Reactome):
Metabolism of proteins: Synthesis of diphthamide-EEF2
Gene Ontology:
Molecular function: 2-(3-amino-3-carboxypropyl)histidine synthase activity; protein binding; 4 iron, 4 sulfur cluster binding
Biological process: protein histidyl modification to diphthamide
Cellular component: 2-(3-amino-3-carboxypropyl)histidine synthase complex; catalytic complex; cytosol; perinuclear region of cytoplasm; protein-containing complex
Genetic constraint (gnomAD): Loss-of-function variants: 28 observed, 42.01 expected, observed/expected ratio (o/e) 0.67, 90% interval 0.49 to 0.91. The upper end of that interval is the gene's LOEUF score, 0.91, which puts it in group 3 of 6, group 1 being the genes least tolerant of losing a copy. Missense variants: 576 observed, 633.24 expected, observed/expected ratio (o/e) 0.91, 90% interval 0.85 to 0.97. Synonymous variants: 279 observed, 269.1 expected, observed/expected ratio (o/e) 1.04, 90% interval 0.94 to 1.14.
Homologues: Orthologues: chimpanzee DPH2 (99% identical), macaque DPH2 (97% identical), pig DPH2 (89% identical), rabbit DPH2 (88% identical), dog DPH2 (86% identical), guinea pig DPH2 (86% identical), mouse Dph2 (84% identical), rat Atp6v0b (84% identical), tropical clawed frog dph2 (43% identical), zebrafish dph2 (40% identical), Drosophila melanogaster Dph2 (28% identical), Caenorhabditis elegans dph-2 (28% identical). Paralogues in human: DPH1 (23% identical).
Diseases named in the same sentence as DPH2 in open-access papers:
DPH2 is named in the same sentence as 13 diseases in open-access papers, as found by Europe PMC text mining. Sharing a sentence is not in itself a finding about the gene and the disease. The quoted sentences say what the papers report.
developmental delay (2 papers, 2024 to 2025). "Loss-of-function (LoF) mutations in genes involved in diphthamide biosynthesis, such as DPH1, DPH2, and DPH5, result in developmental delay (DD), intellectual disability (ID), and multisystemic abnormalities." (PMID 40725455, 2025).
breast carcinoma (1 paper, 2019). "Five genes (DPH2 G3BP1, G3BP2, NSUN2, and TTC17) were similarly regulated by SK1 KD in prostate and breast cancer cells." (PMID 30971929, 2019).
keratitis (1 paper, 2010). A corneal disease that is characterized by inflammation of the cornea. "For example, viral or non viral delivery systems could be used to introduce Dph2(C-) in corneal cells as a local treatment for refractory P. aeruginosa-induced keratitis." (PMID 21203470, 2010).
liver cancer (1 paper, 2023). An epithelial or non-epithelial malignant neoplasm that arises from the liver. "Analysis of liver cancer single-cell data based on TISCH2 showed that DPH2 exhibits low expression in immune-related cells." (PMID 38097948, 2023). "The results of multivariate Cox regression analysis highlighted the significant impact of DPH2 on the prognosis of liver cancer (p = 0.014, hazard ratio > 1)." (PMID 38097948, 2023). "We propose that DPH2 represents a potential target for liver cancer prognosis evaluation and treatment." (PMID 38097948, 2023). "Expression analyses across multiple datasets consistently indicated significant overexpression of DPH2 in liver cancer." (PMID 38097948, 2023).
schizophrenia (1 paper, 2023). A major psychotic disorder characterized by abnormalities in the perception or expression of reality. "As expected, there was also limited concordance between schizophrenia and ADHD (r = 0.0705), particularly for downregulated genes, and six (MAD1L1, KDM4A, IPO13, ATP6V0B, DPH2, PTPRF) of the nine placental genes associated with ADHD were also significantly associated with schizophrenia." (PMID 37188697, 2023).
cancer (4 papers, 2015 to 2024). A tumor composed of atypical neoplastic, often pleomorphic cells that invade other tissues. "In normal tissues, promoter hypermethylation keeps DPH2 expression low, while in cancer tissues, decreasing methylation levels with increasing tumor stage elevate DPH2 expression potentially influencing disease progression." (PMID 38097948, 2023). "The function of CYP2C9, DPH2, EIF2B4, and HEXB on cancer remains unclear, and their biological effects and clinical significance wait for further research in HCC." (PMID 39041652, 2024). "Efficient downregulation of DPH2 and induction of resistance to DT was confirmed in three additional human cancer cell lines derived from different tissues and in a non-transformed human breast epithelial cell line." (PMID 26420058, 2015).
tumor (2 papers, 2015 to 2023). "Analysis shows that normal and low-level tumor-grade samples have higher levels of DPH2 methylation and lower gene expression." (PMID 38097948, 2023). "DPH2 was highly expressed in tumor tissues, while its expression level was low in normal tissues." (PMID 38097948, 2023). "In view of these considerations, how DPH2 gene silencing and in vivo DT selection could impact on maintenance of the biological features and heterogeneity of the tumor should be accurately evaluated in each specific experimental setting." (PMID 26420058, 2015). "We observed a positive correlation between DPH2 expression levels and tumor stage, coupled with a negative correlation between methylation levels and both DPH2 expression and clinical phenotypes." (PMID 38097948, 2023).
DPH2 also shares sentences with these, for which no sentence is quoted: café-au-lait macules (1 paper); colorectal cancer (1); glioblastoma (1); Intellectual disability (1); pancreatic cancer (1); plexiform neurofibroma (1).